EWSR1 (EWS RNA binding protein 1)
Diseases named in the same sentence as EWSR1 in open-access papers (continued):
Sharing a sentence is not in itself a finding about the gene and the disease.
neuronal tumor (2 papers, 2020 to 2022). Neuronal brain tumors are an uncommon group of central nervous system tumors that arise from cells with neuronal differentiation. "EWSR1-rearranged tumors encompass a rare and heterogeneous group of entities with features of the central nervous system (CNS) mesenchymal and primary glial/neuronal tumors." (PMID 35912228, 2022). "The group of CNS mesenchymal (non-meningothelial) and primary glial/neuronal tumors in association with EWSR1-non-ETS rearrangements comprises a growing spectrum of entities, mostly reported in isolation with incomplete molecular profiling." (PMID 32997853, 2020).
renal sarcoma (2 papers, 2022 to 2026). "Our renal case expands the spectrum of EWSR1-rearranged renal sarcomas and represents the second EWSR1-CREM fusion-positive renal case." (PMID 34228212, 2022).
seminoma (2 papers, 2026). A radiosensitive malignant germ cell tumor found in the testis (especially undescended), and extragonadal sites (anterior mediastinum and pineal gland). "Previously misclassified as Sertoli cell tumor, not otherwise specified, or as seminoma, this entity has emerged as a distinct clinicopathologic and molecular subtype defined by recurrent EWSR1::ATF1 gene fusions and a potentially aggressive clinical course." (PMID 41898873, 2026).
spindle cell neoplasm (2 papers, 2023 to 2024). A benign or malignant neoplasm characterized by the presence of neoplastic spindle cells. "ES-RMS with TFCP2 rearrangement is a rare malignant tumor and easily confused with other epithelioid or spindle cell tumors, it may harbor additional gene alteration in addition to TFCP2 rearrangement, such as MET mutation, increased copy numbers of EWSR1 and ROS1 gene, high TMB." (PMID 36998041, 2023).
Splenomegaly (2 papers, 2015 to 2019). Abnormal increased size of the spleen. "Notably though, while the splenomegaly induced by virus recombinants expressing scrambled shRNAs in place of pre-miR-7 and pre-miR-12 stem-loops was substantially reduced (117 mg) compared to wild-type virus, the expression of anti-EWSR1 shRNAs restored this attenuation (159 mg)." (PMID 31363027, 2019).
stomach adenocarcinoma (2 papers, 2022 to 2023). "There are no studies on EWSR1 and PCMT1 to confirm that they are related to the occurrence or prognosis of stomach adenocarcinoma, which can be used as points for further research." (PMID 35686089, 2022).
aneurysmal bone cyst (1 paper, 2021). A locally aggressive and destructive benign cystic lesion of the bone. "In total, through Archer FusionPlex, fluorescence in situ hybridization and/or reverse transcriptase-polymerase chain reaction the EWSR1-NFATC2 rearrangement was identified in 6 of 9 SBC, 3 of 12 benign vascular tumors, and none of 5 aneurysmal bone cyst lacking USP6 fusion." (PMID 34081036, 2021).
benign vascular tumor (1 paper, 2021). "Of the 16 patients with benign vascular tumors, 2 showed the presence of EWSR1-NFATC2 rearrangement in their tumors." (PMID 34081036, 2021). "We here report that the same EWSR1-NFATC2 rearrangement is also recurrent in benign vascular tumors." (PMID 34081036, 2021).
CNS embryonal tumor (1 paper, 2024). "One case of an INI-1 deficient EWSR1-PLAGL1 CNS embryonal tumor has been described, raising the question as to whether this entity overlaps with ATRT." (PMID 38639853, 2024).
depression (1 paper, 2022). "The results showed that compared to HCs, MDD patients had a significantly lower level of MANF and higher levels of ANXA6 and EWSR1, and these molecules were significantly correlated with both TC level and Hamilton Depression Rating Scales (HDRS) score." (PMID 36585419, 2022). "Meanwhile, MANF, EWSR1, and ANXA6 were significantly correlated to TC concentrations and depression severity, and they could be potential biomarkers for diagnosing MDD." (PMID 36585419, 2022). "Besides, MANF, EWSR1, and ANXA6 were found to be significantly altered in the serum of MDD patients and correlated with serum lipid and the severity of depression symptoms." (PMID 36585419, 2022).
dilated cardiomyopathy (1 paper, 2025). Cardiomyopathy which is characterized by dilation and contractile dysfunction of the left and right ventricles. "Consistent with our observations, a recent study has found that overexpression of a fusion Ewsr1-Fli1 protein in mice specifically induces dilated cardiomyopathy by promoting apoptosis in cardiac myocytes." (PMID 41379537, 2025).
dyslipidemia (1 paper, 2022). "Thus, the effect of antidepressants in improving dyslipidemia may be mediated by the MANF/EWSR1/ANXA6 pathway, which is worthy to be investigated in the future." (PMID 36585419, 2022).
embryonic carcinoma (1 paper, 2021). "Analysis of R-loops by DNA:RNA immunoprecipitation followed by next-generation sequencing (DRIP-seq) in a cell line of embryonic carcinoma of the testis (NTERA2) showed that the same sequence in EWSR1 that harbors the breakpoint hotspot forms an R-loop." (PMID 34409300, 2021).
endometrial cancer (1 paper, 2024). Primary or metastatic malignant neoplasm involving the endometrium (mucous membrane that lines the endometrial cavity). "In this study, the EWSR1, which is RNA binding protein, was found to be a common protein in age, myometrial invasion and tumor size, which plays an important role in determining the prognosis of endometrial cancer." (PMID 38894711, 2024). "In summary, our study integrates a complex proteomic landscape into actionable insights for endometrial cancer using the SHAP method for model interpretation—a novel approach that reveals the complex impact of individual proteins such as EWSR1 and MFAP2 on disease subtyping." (PMID 38894711, 2024).
endometrial tumors (1 paper, 2022). "In NGS, the microsatellite (MS) loci, including EWS RNA-binding protein 1, paired box 8, and MYB, also showed instability in endometrial tumors." (PMID 36142641, 2022).
essential tremor (1 paper, 2014). A relatively common disorder characterized by a fairly specific pattern of tremors which are most prominent in the upper extremities and neck, inducing titubations of the head. "We sequenced the exons coding the NES domains of five RNA-binding proteins (TARDBP, hnRNPA2B1, hnRNPA1, TAF15 and EWSR1) that have been previously implicated in neurodegeneration in a series of 257 essential tremor (ET) cases and 376 healthy controls." (PMID 25375143, 2014).
extraventricular neurocytoma (1 paper, 2025). "It was initially classified as an extraventricular neurocytoma by an external service based on its low-to-intermediate grade, small, monomorphic epithelioid cells with clear cell morphology – a diagnosis not previously associated with EWSR1::PATZ1 fusions." (PMID 40575153, 2025).
fibroblastic tumor (1 paper, 2023). "EWSR1::SMAD3–positive fibroblastic tumor (ESFT) is a benign neoplasm defined by a fusion of exon 7 of EWSR1 with exon 5 of SMAD3." (PMID 36983010, 2023).
ganglioneuroblastoma (1 paper, 2016). A neuroblastic tumor characterized by the presence of neuroblastic cells, ganglion cells, and a stroma with Schwannian differentiation constituting more than fifty-percent of the tumor volume. "The continued presence of EWSR1 rearrangement in both the blue round cell component and the ganglioneuroblastoma-like component was shown by FISH analysis." (PMID 27506465, 2016).
gastric tumors (1 paper, 2025). "Most gastric tumors with EWSR1/FUS::CREB fusions have been reported to be CCSLGT, also known as gastrointestinal neuroectodermal tumors (GNETs)." (PMID 40242428, 2025).
kidney tumor (1 paper, 2025). "Next-generation sequencing (NGS) molecular analysis of the kidney tumor showed a type II EWSR1:FLI1 gene fusion between exon 7 of EWSR1 and exon 5 of FLI1." (PMID 40416106, 2025).
latent infection (1 paper, 2019). "On the other hand, latent infection was fully restored to wild-type levels (1 in 320) in mice infected with viruses expressing anti-EWSR1 shRNAs." (PMID 31363027, 2019). "To determine the role of EWSR1 repression during latent infection, we inoculated wild-type B6 mice with MHV68.EW.shR or MHV68.SC.shR, or with parental wild-type virus MHV68.WT, and then quantified features of chronic infection, including spleen weights and the frequency of latently infected cells." (PMID 31363027, 2019). "Repression of EWSR1 modulates latent infection of germinal center B cells." (PMID 31363027, 2019).
malignant peritoneal mesothelioma (1 paper, 2025). An aggressive malignant mesothelioma that arises from the peritoneum. "Recently, pediatric malignant peritoneal mesothelioma cases have been genetically studied, with alterations observed in ALK, EWSR1, FUS1, YY1, or in AURKA, AURKC, HLA-1B, ZNF-217, OR5F1, and MEN1 genes, but not in BAP1." (PMID 40725095, 2025).
mesothelial tumors (1 paper, 2024). "We demonstrated herein that EWSR1/FUS::ATF1 fused tumors should probably be considered as distinct mesothelial tumors." (PMID 39059063, 2024).
neuroendocrine neoplasm (1 paper, 2021). Endocrine tumors, also referred to as neuroendocrine tumors (NETs), are defined by a common phenotype which is characterized by the expression of general markers (neuron specific enolase, chromogranin, synaptophysin) and hormone secretion products. "That of course does not mean that testing for EWSR1 rearrangement should be routinely performed in the workup of suggested neuroendocrine neoplasms." (PMID 34698236, 2021).
oral cancer (1 paper, 2015). "In addition, our results also suggested interaction of hnRNPD with other RNA binding proteins (RBPs) such as ELAVL1, RALY, EWSR1 and FUS in oral cancer." (PMID 26318153, 2015).
osteogenesis imperfecta (1 paper, 2024). Osteogenesis imperfecta (OI) comprises a heterogeneous group of genetic disorders characterized by increased bone fragility, low bone mass, and susceptibility to bone fractures with variable severity. "In addition, somatic mutations in CREB3L1 contribute to osteogenesis imperfecta (OI), while the generation of Fused in sarcoma (FUS)-CREB3L1 and EWS RNA Binding Protein 1 (EWSR1)-CREB3L1 lead to LGFMS and sclerosing epithelioid fibrosarcoma (SEF) respectively." (PMID 38164349, 2024).
pancreatic neuroendocrine neoplasm (1 paper, 2021). A neoplasm with neuroendocrine differentiation that arises from the pancreas. "Further, in a landmark study of 102 cases of pancreatic neuroendocrine neoplasms subjected to whole-genome sequencing, EWSR1 gene fusions were seen in a small percentage (3%); these included novel fusions such as BEND2 as well as one case of EWSR1 exon 7–FLI1 exon 6 gene fusion." (PMID 34698236, 2021).
papillary thyroid carcinoma (1 paper, 2022). "The Ewing sarcoma breakpoint region 1 (EWSR1) rearrangements with unknown genes were detected in a high percentage of classic variants of papillary thyroid carcinoma." (PMID 34374640, 2022).
paraganglioma (1 paper, 2024). A benign or malignant neoplasm arising from paraganglia located along the sympathetic or parasympathetic nerves. "Review of the depicted histological images in a recently reported paraganglioma with EWSR1::CREM fusion showed overlapping features with our cases." (PMID 39031200, 2024).
pleuropulmonary blastoma (1 paper, 2025). A malignant neoplasm affecting the lungs and/or the pleura. "In this study, the identification of an EWSR1::ERG gene rearrangement in a case of pleuropulmonary blastoma—a finding not previously reported in this tumor type—underscores the evolving role of molecular profiling in refining diagnosis and understanding tumor biology." (PMID 40868080, 2025).
poliovirus infection (1 paper, 2022). An disease or disorder caused by infection with Enterovirus C. "The cytoplasmic punctae of EWSR1 in infected cells were highly reminiscent of the development of stress granules upon poliovirus infection." (PMID 36306280, 2022).
retinoblastoma (1 paper, 2022). A malignant tumor that originates in the nuclear layer of the retina. "In addition, immunohistochemistry (IHC) showed positive staining for CD34 and heterogeneous retinoblastoma deficiency, and fluorescence in situ hybridization (FISH) showed no amplification of mouse double minute 2 homolog and no rearrangement of FUS or EWSR1." (PMID 36439417, 2022).
schizophrenia (1 paper, 2008). A major psychotic disorder characterized by abnormalities in the perception or expression of reality. "Consistent with previous studies 3 genes, MTMR9, EWSR1 and NFκβα were altered in the same direction in the post-mortem STG tissue and the peripheral blood lymphocytes (PBLs) from a separate cohort of individuals with schizophrenia identified in a previous study." (PMID 18445270, 2008).
sex cord tumors (1 paper, 2026). "Molecular analyses have revealed that most inflammatory and nested testicular sex cord tumors harbour EWSR1 rearrangements and/or EWSR1::ATF1 gene fusions." (PMID 41384702, 2026).
tauopathy (1 paper, 2018). Neurodegenerative disorders involving deposition of abnormal tau protein isoforms (tau proteins) in neurons and glial cells in the brain. "Interestingly, the third group of proteins whose association with tau increased in the 2.5 m mice was nucleotide binding proteins; these include RBPs such as EWSR1, TAF15 and HNRNPA0, which we previously reported to co-localize with tau pathology in the rTg4510 model of tauopathy." (PMID 30068389, 2018).
testicular neoplasm (1 paper, 2024). Tumors or cancer of the TESTIS. "Finally, a distinctive aggressive testicular neoplasm carrying a EWSR1::ATF1 fusion has been reported recently under the descriptive name “inflammatory and nested testicular sex cord tumor”." (PMID 39031200, 2024).
uterine tumours (1 paper, 2025). "The EWSR1::CTBP1 gene fusion has never previously been reported in uterine tumours, having been reported in the literature only once, in the context of a gastroblastoma." (PMID 41073540, 2025).
vascular malformation (1 paper, 2021). A non-neoplastic disorder that is the result of defects of vascular morphogenesis. "In addition to a series of SBCs occurring in the long bones of young patients, we describe 2 elderly patients presenting with vascular malformations carrying EWSR1-NFATC2 rearrangement, which were multifocal in 1 patient." (PMID 34081036, 2021). "Three vascular malformations of 2 patients revealed EWSR1-NFATC2 rearrangements." (PMID 34081036, 2021). "Using careful mapping of the FISH results within the morphologic context, the EWSR1-NFATC2 fusion was shown to be localized in the lining cells as well as in the spindle cells in the stroma surrounding the spaces, suggesting that both of these are neoplastic in vascular malformations." (PMID 34081036, 2021).
tumor (494 papers, 1999 to 2026). "Several reports have described myxoid variants of EWSR1::CREB fused neoplasms in soft tissue and intrathoracic location." (PMID 40748380, 2025). "While anecdotal and not yet quantified in large cohorts, these findings suggest a selective advantage for complete WT EWSR1 loss during tumor evolution, consistent with the zebrafish and cell line data." (PMID 41301081, 2025). "In the following year, Ma and colleagues further investigated the underlying mechanisms and suggested that HCC tumor cells upregulated the uptake of LA through the LINC01116/EWS RNA-binding protein 1 (EWSR1)/PPARA/FABP1 axis." (PMID 40868150, 2025). "In a Mitf loss-of-function mutational background, Ewsr1::Atf1 mouse tumor formation was slightly delayed." (PMID 38916046, 2024). "WES of 79 rare tumors revealed the EWSR1 gene modified as a fusion, translocation, or nonsense mutation in 22% of the rare tumor cohort." (PMID 38347552, 2024). "Due to formation of the EWSR1/FLI1 fusion gene in the tumor genome, the cell loses one wild type EWSR1 allele." (PMID 36875767, 2023). "The disease is characterized by a morphologically heterogeneous tumor, mainly caused by chromosomal aberrations in the EWSR1 and other genes." (PMID 37709831, 2023). "Unexpectedly, the tumor shows TFCP2 rearrangement with coexistence of increased copy numbers of EWSR1 and ROS1 gene and MET gene mutation." (PMID 36998041, 2023). "Recently, it has been proposed that fusion protein levels can fluctuate in individual tumor cells, generating specific genetic profiles that are associated with EWSR1::FLI1 high and low levels and that in turn are associated with different cell behaviors." (PMID 37511533, 2023). "To gain further insight into the behavior of these tumors, we analyzed a spectrum of EWSR1/FUS::NFATC2-rearranged neoplasms and discuss their radiologic, diagnostic, and molecular features in relation to their prognosis." (PMID 36555836, 2022). "This fact can suggest that the loss of the EWSR1 gene from neoplastic cells of m-PTC can be perceived as a secondary aberration that accumulates during tumor evolution, probably as a result of genome instability." (PMID 34374640, 2022). "To gain further insights into the behavior of these tumors, we analyzed a spectrum of EWSR1/FUS::NFATC2-rearranged neoplasms and discuss their key diagnostic and molecular features in relation to their prognosis." (PMID 36555836, 2022). "Diffuse membranous CD99 immunoreactivity is a hallmark of this tumor and more than 90% of tumors were reported to have EWSR1/FUS-ETS." (PMID 34749732, 2021). "This series demonstrates the importance of FISH and RT–PCR as ancillary diagnostic tools in the diagnosis of EWSR1-rearranged neoplasms." (PMID 28141799, 2017). "Array based-comparative genomic hybridization (a-CGH) confirmed the tumor had numerous chromosome copy number losses, including 11p15.5-p11.12 and 22q12.1-q13.33, with loss of the EWSR1 and WT1 gene regions." (PMID 27403364, 2016). "EWSR1/ETV1 and EWSR1/ETV4 in association with EWSR1/FEV play an important role in influencing the neoplasm localization." (PMID 23329308, 2013). "This tumor is characterized by a chromosomal translocation that fuses the 5′ portion of the EWSR1 gene (encoding the EWS protein) on chromosome 22, in frame, to the 3′ portion of the FLI1 gene (encoding the FLI protein) on chromosome 11." (PMID 23527175, 2013). "It is a type of a poorly differentiated tumour known to be associated with a the expression of EWSR1–ETS fusions or rarely other chimeras." (PMID 23880362, 2013). "However, in addition to the EWSR1::VGLL1fusion, our patient’s tumor had a nonsense mutation in LZTR1, oneof the two genes with germ-line mutations implicated in non-NF2 associatedschwannomatosis." (PMID 41522855, 2026). "Further functional studies will be necessary to determine whether EWSR1 loss influences tumor evolution or SHH pathway dependence in CS." (PMID 41419593, 2025).